INS (insulin)
Diseases named in the same sentence as INS in open-access papers (continued):
Sharing a sentence is not in itself a finding about the gene and the disease.
diabetes (continued). "The majority of participants were women (65%), the mean age was 61.5 ± 12.0 years, the mean duration of diabetes was 19.6 ± 8.7 years, and the median time since insulin initiation was 6 (3.25–10) years." (PMID 30116737, 2018). "Eighty-seven percent of participants in UC at baseline were prescribed diabetes medication (46% prescribed insulin), and 82% were obese." (PMID 29417495, 2018). "There are limited data on cost-effectiveness through administration of a well-balanced nutritional diet aimed at individuals with diabetes in relation to insulin requirements, physician care, dental conditions, and overall signs of inflammation." (PMID 29970834, 2018). "Capsicum has been shown to help improve metabolism and hormone function, diabetes, and reduce insulin and leptin resistance." (PMID 30123516, 2018). "Increased levels of glucose and insulin, in the fasting and postprandial state, and HbA1c are key characteristics of type 2 diabetes mellitus." (PMID 29018885, 2018). "We showed previously that the neuropathological features of Alzheimer’s disease (AD were reduced in patients with diabetes who were treated with insulin and oral antidiabetic medications." (PMID 30383799, 2018). "In our case, we reduced the amount of steroid because our patient had uncontrolled diabetes on self-injection of insulin." (PMID 29914537, 2018). "Classically, pioglitazone has an insulin-sensitizing effect and is widely used clinically to treat type 2 diabetes mellitus." (PMID 29791472, 2018). "This study provides epidemiologic evidence for a new pathway to dementia that is characterized by low fasting serum insulin and differs from the metabolic pathway via hyperinsulinemia or diabetes mellitus." (PMID 29997193, 2018). "Diabetes mellitus is a metabolic syndrome, which comprises an impaired insulin production and action." (PMID 30463839, 2018). "Instead women worried about being unable to live an ordinary life and being bound to lifestyle changes, particularly diet, developing diabetes and needing insulin injections." (PMID 29402265, 2018). "Taken together, there is a strong relationship between iron metabolism and diabetes-induced AD in terms of the improvement in insulin resistance and the clearance of Aβ in the AD brain." (PMID 30043289, 2018). "Patient adherence to insulin is an important criterion for achieving the desired therapeutic outcomes in diabetes management." (PMID 29520741, 2018). "In regression analysis, age, BMI, waist circumference, hypertension, fasting insulin, testosterone, SHBG, FAI, and family history of diabetes were significant factors associated with glucose intolerance." (PMID 29707577, 2018). "Sitagliptin and vildagliptin have been shown to improve insulin sensitivity in patients with type 2 diabetes mellitus (T2DM)." (PMID 29970184, 2018). "In long-term follow-up, patients with ketosis-prone diabetes separate into those who continue to require insulin treatment and those who can be treated to near-normoglycemia with diet alone or diet plus oral agents." (PMID 30280274, 2018). "Accordingly, DM is classified into either type 1 diabetes mellitus (T1DM) which is insulin dependent or type 2 diabetes mellitus (T2DM) which is non-insulin dependent." (PMID 29844959, 2018). "SLC2A1 (GLUT1) and SLC2A3 (GLUT3) genes were involved in glucose and insulin metabolism which played vital role in development of obesity, diabetes and CRC." (PMID 29876008, 2018). "Critically, β cell-specific double KO (Eed −/−; Mll −/−) littermates were largely protected from diabetes, exhibiting improved glucose tolerance and insulin secretion at 25 weeks of age." (PMID 29754954, 2018). "The other type of diabetes indication includes insulin-targeting cells are insensitive to insulin even though insulin is present in body." (PMID 30046337, 2018).
diabetes (continued). "Risk factors associated with diabetic retinopathy include age, race/ethnicity, longer duration of diabetes, insulin dependence, younger age of diabetes onset, higher HbA1c, insulin treatment and higher blood pressure." (PMID 29623345, 2018). "Hypoglycemia in patients with diabetes, defined as blood glucose below 70 mg/dl, is one of the most common adverse events in patients taking insulin or oral hypoglycemic agents." (PMID 30473710, 2018). "Prevalence was lowest in Alaska and highest among patients with A1c >/ = 8%, duration of diabetes > 10 years, or using insulin." (PMID 29924846, 2018). "Diabetes remitted after 10 months with an uneventful course and good psychomotor development under subcutaneous insulin regimen." (PMID 28943514, 2018). "In fact, miR-7 has been extensively related to diabetes impairing insulin secretion and beta cell dedifferentiation." (PMID 29808089, 2018). "Most patients with diabetes were treated with metformin constituting 60.5% of the group, while 22% were on insulin." (PMID 29402218, 2018). "In the pathophysiology of diabetes including mitochondrial diabetes, apoptosis of β-cells plays important roles in impaired insulin secretion." (PMID 29942356, 2018). "Failure to secrete sufficient amounts of insulin results in diabetes mellitus, a common pathology with serious long-term complications that affect several tissues." (PMID 29773801, 2018). "MODY is a form of diabetes classically presents as non-insulin-requiring diabetes in lean individuals typically younger than 25 with evidence of autosomal dominant inheritance." (PMID 29487566, 2018). "Patients with advanced diabetes, who are more likely to require insulin therapy, consume the majority of the resources." (PMID 29682315, 2018). "The study performed in a large group of patients with type 2 diabetes mellitus proved that premixed insulin both analogue and human are efficient and safe, and studied patients were satisfied with the treatment method." (PMID 29755520, 2018). "Nevertheless, these animals show increased insulin sensitivity in skeletal muscle, liver and adipose tissue accompanied by protection from streptozotocin-induced diabetes." (PMID 30002646, 2018). "The protein tyrosine phosphatase PTP1B, which is a negative regulator of insulin and leptin signaling, is a highly validated target for therapeutic intervention in diabetes and obesity." (PMID 29348454, 2018). "In diabetes mellitus either insufficient amounts of insulin is secreted by pancreatic islet cells of Langerhans or there is insulin resistance leading to an increase in blood glucose level." (PMID 30545352, 2018). "The vast majority of older adults with diabetes have type 2 diabetes (>90%), owing to a combination of increased insulin resistance and impaired insulin secretion." (PMID 29417185, 2018). "Diabetes mellitus (DM) is a condition in which there are increased glucose levels in the blood due to the inefficiency of the pancreas in producing enough insulin, or the inability of the body to use it effectively." (PMID 30360409, 2018). "Due to the progressive nature of diabetes and β-cell dysfunction, insulin replacement therapy is frequently required in T2DM patients." (PMID 29527102, 2018). "We analysed a dataset used in a recent network meta-analysis of severe hypoglycaemic events conducted to inform National Institute for Health and Care Excellence recommendations regarding basal insulin choice for patients with type 1 diabetes mellitus." (PMID 29445964, 2018). "Diabetes mellitus (DM) is a metabolic disease characterized by hyperglycemia due to defects in insulin secretion and/or impaired biological effects." (PMID 30298008, 2018). "Diabetes is characterized by defects in the secretion or signaling of insulin that results in the impairment of glucose uptake and ensuing high plasma glucose levels." (PMID 30564582, 2018).
diabetes (continued). "In the Global Attitudes of Patients and Physicians in Insulin Therapy for Diabetes Mellitus (GAPP) Survey, 8.6% of subjects omitted insulin doses because of pain associated with the injection." (PMID 30116737, 2018). "Practically, insulin resistance exists throughout the course of diabetes; thus, enhancing insulin sensitivity is a key strategy for treatment." (PMID 29744368, 2018). "Patients with type 2 diabetes mellitus had 34% higher fasting plasma glucose, 28% higher fasting insulin, and 29% higher fasting C-peptide." (PMID 30190473, 2018). "It is also becoming increasingly well-recognized that podocyte insulin responses are dysregulated in conditions of systemic metabolic dysfunction, including diabetes, contributing towards albuminuria in these settings." (PMID 30524379, 2018). "The epidemic evidences of worldwide rapid rise in prevalence of obesity and diabetes have focused efforts on development of intervention strategies which both sensitize insulin action and produce sustained improvements in β cell function." (PMID 30459598, 2018). "High BCAA levels in subjects with defective insulin secretion were first described in dogs with experimental diabetes." (PMID 29755574, 2018). "This understanding of the diabetes optimization objectives led to quantitative description of the glucose-insulin control network, modeling, simulation and, ultimately, to bioengineering control of diabetes." (PMID 32232090, 2018). "The topics were approaches to problem solving, basic guidelines for the management of DM (transitioning from paediatric to adult care, signs of acute and chronic complications of diabetes) and the use of insulin pump therapy." (PMID 30532235, 2018). "Subcutaneous administration of insulin is a conventional method for the management of diabetes mellitus." (PMID 30524677, 2018). "The effect of integrated diabetes care programs on HbA1c was different for people on insulin therapy." (PMID 29405097, 2018). "Body weight reduction, water intake increasing, hyperglycemia, and insulin level reduction have been considered as the typical characteristics of diabetes." (PMID 29853958, 2018). "Social stigma attached to insulin injections as a form of drug abuse is another important feature of stigmatization in living with diabetes (Berlin, Sass, Davies, Reupert, & Hains, 2005)." (PMID 29599986, 2018). "Diabetes-induced increase in food and water intake was also significantly (p < 0.05) reduced by insulin treatment (10 IU/kg) when compared with diabetic wound control rats." (PMID 29805347, 2018). "Individuals who developed diabetes during follow-up were older and had higher fasting levels of glucose and insulin, higher BMI, a more sedentary lifestyle, higher protein intake and lower fibre intake." (PMID 29796113, 2018). "Hypoglycaemia is a common, unpredictable and potentially dangerous side effect of insulin therapy for diabetes." (PMID 28803366, 2018). "Since pancreatic beta cells play an essential role in insulin production, a dysfunctional response in this cell type unsurprisingly has been contributed to the pathogenesis of diabetes." (PMID 30054761, 2018). "Diabetes mellitus (DM) is a chronic metabolic disease characterized by hyperglycemia secondary to dysregulated insulin activity." (PMID 30558542, 2018). "Studies have already demonstrated that repeated daily injection of insulin in patients with diabetes affects patients’ well-being and there is a search for alternative modes of administration." (PMID 29976222, 2018). "Another key finding is that insulin secretion rather than insulin action decreases with number and type of family member affected with the lowest levels of insulin secretion in individuals with combination of ≥ 3 siblings and parents with diabetes." (PMID 29274011, 2018).
diabetes (continued). "The benefits of physical activity in the prevention or management of diabetes are already well established, reducing mortality and complications through better glycemic control and improved insulin sensitivity." (PMID 30522580, 2018). "It is known that persistence of even a low degree of endogenous insulin secretion in patients with long-standing T1D leads to fewer (severe) hypoglycemic episodes, fewer diabetes-related complications, and a lower HbA1c." (PMID 30250968, 2018). "Skeletal muscle is the principal site of glucose uptake and one of the main insulin-responsive organs accounting for the regulation of glucose homeostasis under both healthy and diabetes conditions." (PMID 30199540, 2018). "Coupled with an optimal protocol, the cell line consistently created highly pure, insulin-producing cells capable of reversing diabetes in animal models." (PMID 30183752, 2018). "Apart from identifying a potential causal effect of long-term increased insulin exposure on mammographic dense breast tissue, these findings support efforts to improve screening awareness and participation among insulin-treated patients with diabetes." (PMID 30092829, 2018). "The most common diabetes treatment modality was a combination of oral hypoglycaemic medications and Insulin (n = 11)." (PMID 29636823, 2018). "If the beta cells in the body stop making insulin, blood sugar levels start to rise, which can lead to diabetes." (PMID 30412052, 2018). "The development of type 2 diabetes mellitus (T2DM) involves a reduction in insulin sensitivity with high basal insulin secretion and hyperproinsulinemia." (PMID 29670038, 2018). "The duration of diabetes was shorter in the metformin-only group (median 3.1 years) and longer in the insulin group (median 10.8 years)." (PMID 30055585, 2018). "Our findings thus identify the CD44v-LAT1-insulin axis as a potential target for therapeutic intervention in diabetes." (PMID 29434323, 2018). "Type 1 diabetes mellitus (T1DM) is an autoimmune disease characterized by inadequate insulin secretion, in which the insulin-producing pancreatic beta cells are targeted and destroyed by the immune system." (PMID 30233498, 2018). "AGL1 developed type 1 diabetes mellitus during childhood, and at the moment of this study she had just started insulin treatment." (PMID 30283460, 2018). "For many patients living with Diabetes, day to day control and management requires daily blood sugar measurements and insulin injections." (PMID 30555274, 2018). "Ultimately, diabetes results from insufficient insulin-secreting β cell mass, resulting from impaired function, increased cell death, or loss of cell identity." (PMID 29754954, 2018). "These perturbations challenge the technological treatment of diabetes, which includes real-time warning, alarms, advisory systems, or automated insulin delivery." (PMID 32232090, 2018). "In the different anti-diabetes animal experiments, there is an argument about the level of plasma insulin in modelling animals." (PMID 30273360, 2018). "Pancreatic beta cells play a significant role in maintaining glucose homeostasis by releasing insulin and several microRNAs have been shown to promote apoptosis in beta cells, thereby leading to diabetes (Feng, Xing & Xie, 2016)." (PMID 29922517, 2018). "In the nineteenth century, the nature of diabetes was generally understood, and with the discovery of insulin in 1921 by Frederick Banting at the University of Toronto type 1 diabetes was no longer a death sentence." (PMID 32232090, 2018). "Other studies have also shown that low testosterone and SHBG levels to also predict the development of MetS as well as diabetes and that elevated testosterone and SHBG led to increased insulin sensitivity and reduced risk of MetS." (PMID 30057912, 2018). "Diabetes treatment was similar between the groups: 47.2% and 52.1% for Insulin and 88.7% and 81.6% for hypoglycaemic drugs respectively." (PMID 30479760, 2018).
diabetes (continued). "The serum insulin level in the diabetic control group decreased due to STZ that resulted in diabetes by the rapid depletion of β-cells, which reduced the insulin release." (PMID 29890969, 2018). "Diabetes mellitus (DM) is a metabolic disorder marked by high levels of blood glucose resulting from a defect in insulin production, insulin action or both." (PMID 30477167, 2018). "The DIo, which expresses the capacity of β-cells to compensate adequately for insulin resistance through increased insulin secretion, has been shown to be a predictor of development of diabetes." (PMID 29925523, 2018). "Patients in the insulin stratum tended to be older, with higher BMI, higher HbA1c, higher systolic blood pressure, and a longer duration of diabetes than patients in the metformin stratum." (PMID 30222367, 2018). "One of the best known discoveries made using this model is the identification of ER chaperone GRP170 involved in proinsulin degradation via ERAD in the mutant insulin INS gene-induced diabetes of youth (MIDY) in humans." (PMID 29921793, 2018). "Average duration of diabetes was 9.6 ± 5.7 years, average age of participants was 62.9 ± 9.4 years and median insulin treatment duration was 20 months." (PMID 29563974, 2018). "A characteristic of diabetes is that the pancreas cannot provide sufficient insulin or the body cannot respond properly to insulin." (PMID 29765322, 2018). "The majority of miRNAs associated to glucose homeostasis had target genes significantly over-represented in pathways related to general cellular processes like endocytosis, but also to more diabetes-relevant pathways like insulin signaling." (PMID 29346396, 2018). "The majority of patients were taking metformin and sulphonylureas for their diabetes; one patient required insulin." (PMID 29450844, 2018). "Fatima is a 3-year-old girl who was recently diagnosed with diabetes and started on insulin injections." (PMID 29682577, 2018). "First, due to the high number of patients taking oral diabetes medicines compared to insulin, only patients taking oral diabetes medicines are included." (PMID 30462704, 2018). "Individuals with a combination of ≥ 3 siblings and parents with diabetes presented with the lowest levels of insulin secretion." (PMID 29274011, 2018). "Mean age was 64 ± 12 years (71% males) and 4384 (35%) were diabetic (262 diet/exercise treated, 3342 orally-treated and 780 insulin-treated diabetes)." (PMID 29402330, 2018). "Our results suggest that the CD44v-LAT1-insulin axis is a potential target for the treatment of diabetes." (PMID 29434323, 2018). "The main pathogeneses of type 2 diabetes mellitus are failure of insulin secretion and insulin resistance." (PMID 29862294, 2018). "The reduced expression of insulin signaling genes (such as PI3K and AKT) indicated an elevated risk of diabetes in adulthood." (PMID 30158951, 2018). "Some predictors of the likelihood of postpartum diabetes screening have been described such as older age, ethnicity, insulin use during pregnancy, GDM in a previous pregnancy, higher educational levels, nulliparity, and higher income." (PMID 29308091, 2018). "Further studies would be needed to analyze the effect of the insulin pump on diabetes-related microvascular and cardiovascular complications." (PMID 30410846, 2018). "There is substantial debate about the etiology of these diabetes-induced sensory alterations, including their relation to systemic glucose levels, diabetes-induced vascular changes, peripheral neurodegeneration or neuronal functions of insulin signaling." (PMID 29752280, 2018). "In China, insulin is more widely used to treat patients with type 2 diabetes mellitus (T2DM) compared with many Western countries." (PMID 29862021, 2018). "The management of pre-diabetes includes the combination of dietary and pharmacological interventions to increase insulin sensitivity." (PMID 30011905, 2018).